RRP7A (ribosomal RNA processing 7 homolog A)
Description:
Nucleolar protein that is involved in ribosomal RNA (rRNA) processing. Also plays a role in primary cilia resorption, and cell cycle progression in neurogenesis and neocortex development. Part of the small subunit (SSU) processome, first precursor of the small eukaryotic ribosomal subunit. During the assembly of the SSU processome in the nucleolus, many ribosome biogenesis factors, an RNA chaperone and ribosomal proteins associate with the nascent pre-rRNA and work in concert to generate RNA folding, modifications, rearrangements and cleavage as well as targeted degradation of pre-ribosomal RNA by the RNA exosome.
Synonyms: CGI-96; Rrp7; BK126B4.3; MCPH28
Tractability: Small molecule: a structure with a bound ligand is known. PROTAC: ubiquitination databases record sites on it; its protein half-life has been measured.
Gene: Protein-coding gene on chromosome 22 (42,507,982 to 42,519,853, reverse strand). Ensembl gene ENSG00000189306.
Subcellular location: Nucleus, nucleolus; Cell projection, cilium; Cytoplasm, cytoskeleton, microtubule organizing center, centrosome
Subcellular location (Human Protein Atlas): Nucleoli; Cell Junctions; Nucleoplasm
Pathways (Reactome):
Metabolism of RNA: Major pathway of rRNA processing in the nucleolus and cytosol; rRNA modification in the nucleus and cytosol
Gene Ontology:
Molecular function: protein binding; RNA binding; nucleic acid binding
Biological process: cilium disassembly; protein localization to nucleolus; ribosomal small subunit biogenesis; ribosome biogenesis; rRNA processing; maturation of SSU-rRNA
Cellular component: centrosome; cilium; nucleolus; small-subunit processome; CURI complex; nucleoplasm; UTP-C complex; cytoplasm
Genetic constraint (gnomAD): Loss-of-function variants: 27 observed, 28.53 expected, observed/expected ratio (o/e) 0.95, 90% interval 0.7 to 1.3. The upper end of that interval is the gene's LOEUF score, 1.3, which puts it in group 5 of 6, group 1 being the genes least tolerant of losing a copy. Missense variants: 318 observed, 278.58 expected, observed/expected ratio (o/e) 1.14, 90% interval 1.04 to 1.25. Synonymous variants: 120 observed, 109.92 expected, observed/expected ratio (o/e) 1.09, 90% interval 0.94 to 1.27.
Homologues: Orthologues: macaque RRP7A (94% identical), guinea pig RRP7A (88% identical), pig RRP7A (86% identical), rat Rrp7a (84% identical), mouse Rrp7a (84% identical), rabbit RRP7A (78% identical), dog RRP7A (63% identical), tropical clawed frog rrp7a (57% identical), zebrafish rrp7a (45% identical), Drosophila melanogaster CG9107 (35% identical), Caenorhabditis elegans ZC434.4 (24% identical).
Diseases named in the same sentence as RRP7A in open-access papers:
RRP7A is named in the same sentence as 16 diseases in open-access papers, as found by Europe PMC text mining. Sharing a sentence is not in itself a finding about the gene and the disease. The quoted sentences say what the papers report.
microcephaly (4 papers, 2020 to 2024). A congenital or acquired developmental disorder in which the circumference of the head is smaller than normal for the person's age and sex. "A similar delay in cell cycle progression, together with impaired ciliary resorption, has recently been reported for a protein so far not known to be associated with primary cilia or centrosomes: Surprisingly, ribosomal RNA processing 7 homolog A (RRP7A) is a newly identified microcephaly gene." (PMID 34744618, 2021). "Thus, the results support that the microcephaly phenotype is specific to mutation of rrp7a and importantly, that the phenotype–genotype relationship observed in the Pakistani family is replicated in the zebrafish model." (PMID 33199730, 2020). "The RRP7A is also a microcephaly disease gene evidenced from patient-derived cells with defects in cell cycle progression and primary cilia resorption." (PMID 38045239, 2024). "The RRP7A protein is localized to both nucleoli and primary cilia and, indeed, a delay in ciliary resorption has been observed in microcephaly patient-derived dermal fibroblasts." (PMID 34744618, 2021). "The wild-type zebrafish rrp7a mRNA, but not mRNA encoding Rrp7a W152C mutant protein partially rescued the microcephaly phenotype." (PMID 33199730, 2020). "Injection of wild-type fertilized oocytes with an antisense morpholino oligonucleotide (MO) designed to interfere with rrp7a mRNA splicing resulted in phenotypes similar to the rrp7a−/− mutants, supporting that the microcephaly phenotype in mutants is specific to rrp7a." (PMID 33199730, 2020). "In addition, we observed higher levels of processing intermediates in the rrp7a+/− in cross embryos displaying a microcephaly phenotype (right)." (PMID 33199730, 2020). "The microcephaly phenotype could be rescued with injection of wild-type rrp7a mRNA, but injection with rrp7a W152C mutant mRNA failed to save the phenotype." (PMID 33199730, 2020).
Primary microcephaly (2 papers, 2020 to 2022). Head circumference below 2 standard deviations below the mean for age and gender at birth. "Zebrafish embryos, homozygous for a truncating mutation in rrp7a, presented with significantly reduced size of the forebrain, resembling the clinical features of primary microcephaly." (PMID 33199730, 2020). "Ribosomal RNA Processing 7 Homolog A (RRP7A) localises to primary cilia, and mutations in the gene encoding RRP7A cause primary microcephaly—a disorder characterised by decreased brain size and intellectual disability." (PMID 36547474, 2022).
colon carcinoma (1 paper, 2020). "In siRNA knockdowns of RRP7A in HeLa cells, primary lung fibroblasts, and HTC-116 colon carcinoma cells, the phenotype was characterized as “21S down, 18S-E down”33." (PMID 33199730, 2020).
glioma (1 paper, 2022). A benign or malignant brain and spinal cord tumor that arises from glial cells (astrocytes, oligodendrocytes, ependymal cells). "Moreover, analysis of genes and proteins that interact with KIF18A showed that several molecules related to cell cycle and cell division, such as RRP7A, ANAPC4, WEE1, CDC20, and NDC80, were enriched in glioma." (PMID 35591854, 2022).
Pasteurella multocida infection (1 paper, 2023). "It was also found that P0910 and ΔOmpH in Pasteurella multocida infection activated the expression of ropE, HSPBP1, FERH, ATP10A, ABCA13, RRP7A, IL-10, IFN-γ, IL-17A, EGFR and dnaJ." (PMID 36977260, 2023).
cancer (1 paper, 2022). A tumor composed of atypical neoplastic, often pleomorphic cells that invade other tissues. "Among the two genes that have not been previously linked to cancer (GXYLT1 and RRP7A), GXYLT1 was recurrently mutated in 18 of 45 samples (40%)." (PMID 35459861, 2022).
neurodevelopmental disorder (1 paper, 2020). A behavioral and cognitive disorder with onset during the developmental period that involves impaired or aberrant development of intellectual, motor, or social functions. "As defective ribosome biogenesis is associated with cell cycle defects as well as neurodevelopmental disorders in combination with additional abnormalities, we investigated if the p.W155C mutation in RRP7A affects pre-rRNA processing using patient-derived (human) dermal fibroblasts (HDFs)." (PMID 33199730, 2020).
RRP7A also shares sentences with these, for which no sentence is quoted: amoebiasis (1 paper); anorexia nervosa (1); autosomal recessive primary microcephaly (1); depression (1); Infertility (1); Intellectual disability (1); schizophrenia (1); teratocarcinoma (1); tumor (1).